MMP9 (matrix metallopeptidase 9)
Diseases named in the same sentence as MMP9 in open-access papers (continued):
Sharing a sentence is not in itself a finding about the gene and the disease.
prostate carcinoma (continued). "Moreover, there is evidence that S100A4 controls the invasive potential of human prostate cancer cells through the regulation of MMP9 expression, thus contributing to the invadopodia-mediated proteolytic degradation of ECM components." (PMID 24379889, 2013). "A recent study in prostate cancer suggests that MMP9 is induced through a PI3K/NF-κB pathway." (PMID 24340014, 2013). "Curcumin suppressed MMP2 and MMP9 activity in the tumor bearing site of prostate cancer." (PMID 24216994, 2013). "In this study, we investigated whether SKIP regulates the TGF-β1-induced extracellular matrix degrading system uPA/PAI-1 and MMP-9 expression in prostate carcinoma PC-3 cell line." (PMID 23766912, 2013). "Activation of AhR induces transcription of MMP-9 in advanced prostate cancer cells." (PMID 25068070, 2013). "Notably, S100A4 can promote invasive ability of prostate cancer cells through MMP9 and TIMP1 regulation." (PMID 23383075, 2013). "Interestingly, the interaction between CD44 and Mmp9 in PC3 prostate cancer cells has been demonstrated to be induced by Spp1." (PMID 24304664, 2013). "Small molecule Mmp9 inhibitors are currently in clinical trials for Multiple Sclerosis, Chronic Obstructive Pulmonary Disease and Prostate Cancer, and may aid the pursuit of Mmp9 inhibition during tendon healing." (PMID 22792383, 2012). "MMP9 is expressed and secreted from both prostate cancer cells and their microenvironment." (PMID 22074556, 2011). "We showed that CXCL12 is required for SLUG-mediated MMP9 expression in prostate cancer cells." (PMID 22074556, 2011). "Inhibition of MMP-2 and MMP-9 expression suppress the metastatic potential of prostate cancer." (PMID 21629786, 2011). "In prostate cancer cells, down-regulation of MMP9, but not MMP2 is consistent with the loss of the invasion/metastasis phenotype." (PMID 20717117, 2010). "In addition to its direct proteolytic action on ECM substrates, MMP-26 has also been reported to be an activator of proMMP-9 in prostate cancer cells and correlated to MMP-9 activity in esophageal carcinoma." (PMID 20074375, 2010). "NFκB-mediated expression of genes, involved in angiogenesis (IL-8, VEGF), invasion and metastasis (MMP-9, uPA, uPA receptor), may further contribute to the progression of prostate cancer." (PMID 18226269, 2008). "The coordinated regulation of proteins such as OPN, αvβ3, RANKL, CD44, and MMP-9 may provide a physiological mechanism for prostate cancer cells to promote migration during metastasis." (PMID 17343740, 2007). "The present study supports the hypothesis that OPN/αvβ3 signaling-mediated CD44/MMP-9 complex formation on the cell surface, MMP-9 secretion, and activity may play important roles in prostate cancer cell migration." (PMID 17343740, 2007). "CD44/MMP-9 complex formation on the cell surface may represent a unique motility-enhancing signal in prostate cancer cells, thereby promoting their invasiveness." (PMID 17343740, 2007). "Clinically, elevated MMP-9 levels, whether in tumor tissue or circulation, correlate with poor prognosis, increased metastatic potential, and therapeutic resistance across malignancies including breast, colorectal, lung, and prostate cancers." (PMID 41304763, 2025). "Additionally, MMP9 is upregulated in breast, prostate cancers, bladder cancer, and colorectal cancer, suggesting that the upregulation of MMP9 may be influenced by the overexpression of these co-activators." (PMID 39343952, 2024). "Thus, the expression levels of IRS-2 and MMP-9 were examined in human prostate cancer tissues." (PMID 37894751, 2023). "In addition, the finding that MMP-9 plays a key role in IGF signal pathway activation in PC3 cells could provide a novel strategy for improved prostate cancer diagnosis and treatment." (PMID 37894751, 2023). "MMP9 might be the most important in tumor invasion and metastasis, especially in prostate cancer." (PMID 30889876, 2019).
prostate carcinoma (continued). "HLE also caused apoptosis and repressed the migration and invasion of human prostate cancer LNCaP cells by inhibiting the activity and expressions of matrix MMP-9 causing NF-κB inactivation mediated via inhibition of the protein kinase B (Akt)/NF-κB/MMP-9 cascade pathway." (PMID 31261861, 2019). "In prostate cancer, MMP-9 may amplify local angiogenesis by cleaving membrane-bound VEGF." (PMID 31921634, 2019). "Additionally, invasion-related effectors MMP2, MMP9, and E-cadherin were down-regulated in the miR-124 transfectants, which might account for the impaired invasive and migratory capabilities of prostate cancer cells with miR-124 overexpression." (PMID 25969668, 2015). "Taken together, the results suggest that CRMP4 down-regulates MMP-9 expression and inhibits Rac1 GTPase by enhancing phosphorylation of Rac1 and Akt through direct interaction with Rac1 and Akt, eventually leading to suppression of prostate cancer invasion and metastasis." (PMID 25888628, 2015). "Our research demonstrated that the expression of CXCL12, CXCR4, MMP-2, and MMP-9 in prostate cancer was much higher than in hyperplastic prostate tissue, implying that these proteins interact with each other and together may regulate chemotactic ability and invasiveness of tumor cells." (PMID 18983683, 2008). "Finally, one must consider the possibility that the increase in CD44 surface expression, MMP-9 activation, and the migration of prostate cancer cells may occur through multiple down stream signaling pathways that are instigated by αvβ3 receptor." (PMID 17343740, 2007). "Accordingly, increased IFN-β expression in prostate cancer cells was found to downregulate osteoclast activation genes like receptor activator of NF-κB (RANK) and matrix metalloproteinase-9 (MMP9) in RAW264.7 precursor cells co-cultured with tumor cells." (PMID 40098954, 2025). "Recently, we showed that IRS-2 promotes the secretion of matrix metalloproteinase-9 (MMP-9) in the PC3 cell line, a malignant prostate cancer cell line expressing high levels of IRS-2." (PMID 39859555, 2025). "The activity of MMP9 and/or MMP2 proenzymes was increased in all representative stages of prostate cancer progression." (PMID 39796768, 2025). "Several natural compounds have demonstrated anti-cancer effects in NSCLC and prostate cancer through concurrent inhibition of MMP2 and MMP9 expressions." (PMID 40779492, 2025). "Consistent with previous research, our RT-qPCR results demonstrated that SChLAP1 knockdown significantly inhibited the expression of invasion markers MMP-9 and MMP-14, as well as the proliferation marker VEGF, in prostate cancer cells." (PMID 39975023, 2025). "The effective inhibition of MMP-2 and MMP-9 activity and cell migration was also verified in DU145 prostate cancer cells using a Psidium guajava leaf extract rich in rutin and quercetin, which were also the dominant components of our tested extracts." (PMID 39683504, 2024). "For instance, SFMBT2 assisted in transcription suppression of MMP9 and MMP26, thereby inhibited metastasis of prostate cancer cells." (PMID 38734627, 2024). "It specifically targets NF-κB, leading to the suppression of PMA- and TNF-α-stimulated MMP-9 and VEGF expression in prostatic carcinoma." (PMID 38611849, 2024). "It promotes invasion in hepatocellular carcinoma and epithelial–mesenchymal transition (EMT) in prostate cancer via MMP-2, MMP-7, MMP-9, and NF-κB signaling." (PMID 39205642, 2024). "Taken together, HA has an efficacy to suppress the migratory and invasion potential of prostate cancer PC3 and LNCaP cells as well as overexpressing RUNX1 in PC3 cells via the downregulation of MMP2 and MMP9." (PMID 37367670, 2023). "Mechanistic studies showed that Co-Sp reduced the expression of cyclin D1, cyclin E, CDK4, CDK2, MMP-9, MMP-1, and Bcl-2, and increased the expression of p21, cleaved caspase-9, cleaved caspase-3, cleaved PARP, and Bax in prostate cancer cells." (PMID 37313467, 2023).
prostate carcinoma (continued). "The addition of SE to in vitro prostate cancer cells reduced MMP-2 and MMP-9 activity and the expression of nuclear transcription factor-kappa B, and increased TIMP-2 activity." (PMID 37623846, 2023). "COL4A6 is highly downregulated in prostate cancer, and its deletion can promote prostate cancer progression and metastasis by activating the p-focal adhesion kinase (FAK)/matrix metallopeptidase 9 (MMP-9) signaling pathway." (PMID 36353536, 2022). "The administration with 18α-GA can prevent the invasion of DU-145 prostate cancer cells by downregulating the levels of NF-ĸB (p65), VEGF and MMP-9, as well as HMGB1 and IL-6." (PMID 36313350, 2022). "Inhibition of SENP1 expression in high-grade metastatic prostate cancer cells can affect the bone remodeling ability of HIF-1α and its downstream matrix metalloproteinase (MMP)-2 and MMP-9, and then inhibit the bone metastasis of prostate cancer cells." (PMID 33791211, 2021). "In human prostate cancer cells, shikonin inhibited cell metastasis by reducing MMP2/MMP9 expression via AKT/mTOR and ROS/ERK1/2 pathways." (PMID 34812264, 2021). "Overexpression of FABP4 in prostate cancer results in the upregulation of MMP-2 and MMP-9, which promotes the invasion of cancer cells." (PMID 34685761, 2021). "Since the inhibitory effect of RSV on MMPs has been shown in many cancer types, and RSV is capable of inhibiting both MMP-2 and MMP-9, the inhibitory effect of RSV on prostate cancer was examined in different models." (PMID 33535458, 2021). "For example, an increase in the expression of the Ca2+ channels TRPV2 in prostate cancer, and TRPM8 in squamous cell carcinoma resulted in induction of MMP-2 and MMP-9, respectively." (PMID 33802790, 2021). "Consistently, AKT was shown to be mainly involved in the secretion of osteolytic factors, such as PTHrP or MMP9, and in the RANKL-mediated activation of osteoclasts in prostate cancer." (PMID 34064589, 2021). "Knock-down of NOTCH1 results in a concomitant decrease of MMP9 expression in prostate cancer cells, and of MMP2 and MMP9 in BrCa cells." (PMID 33430387, 2021). "Release of matrix metalloproteinases by osteoclasts, including MMP-9, has been shown to enhance angiogenesis and thereby aid in growth of PC3 prostate cancer cells in a murine model." (PMID 33805598, 2021). "TCDD and B[a]P also up-regulate MMP-9 in prostate cancer cells, while AHR knockdown decreases invasion of prostate cancer cells in matrigel." (PMID 33396563, 2020). "In another study, prostate cancer cells cultured in 3D hydroxyapatite (HA)-collagen scaffolds exhibited reduced expression of MMP1 and MMP9 compared to 2D culture." (PMID 32967150, 2020). "Silencing of CTBP2 markedly increases apoptosis of prostate cancer cells; decreases the expression of IL-8, AT2R, CCND1, MMP9, MYC, and HSPC111; and reduces tumor growth in mouse xenograft model of human prostate cancer." (PMID 31323811, 2019). "A previous study demonstrated that the CM of human MSCs (hMSCs) promoted the proliferation, migration, and invasion of PC-3 (prostate cancer cells) by upregulating of the expression of matrix metallopeptidase 2 (MMP-2) and matrix metallopeptidase 9 (MMP-9)." (PMID 31569731, 2019). "In case of LNCaP, SFMBT2 interacts with YY1 and represses MMP2, MMP3, and MMP9 and inhibits invasion and migration of prostate cancer cells, and illustrating both pro and anti-role of YY1 in prostate cancer growth." (PMID 31824839, 2019). "Enforced PODXL expression in breast and prostate cancer cell lines promoted the migrated and invasive abilities by increasing expression of MMP-1 and MMP-9, and activating MAPK and PI3K signaling." (PMID 29748877, 2019).
prostate carcinoma (continued). "In a xenograft model of prostatic cancer, Curcumin treatment lead to a significant reduction of MMP-2 and MMP-9 expression, and the inhibition of the invasive ability of the tumor cells in vitro." (PMID 29890744, 2018). "In conclusion, our data suggested that HDGF knockdown inhibits cellular migration and invasion in vitro of prostate cancer via modulating epithelial-mesenchymal transition (EMT) signaling pathway, as well as MMP2 and MMP9 signaling pathway." (PMID 29300772, 2018). "We have shown that embigin contributes to the progression of prostate cancer with multiple cancer behaviors through AMPK/mTORC1/p21WAF1 and NF-κB/MMP9 signaling." (PMID 30041429, 2018). "Curcumin-treated prostate cancer cells (DU-145) had significantly reduced MMP-2 and MMP-9, along with impaired in vitro cellular invasion." (PMID 29890744, 2018). "In order to characterize ongoing bone cell activity in clinical cases of prostate cancer bone metastasis, we selected a set of genes to represent osteoclast activity (ACP5, CTSK, MMP9), osteoblast activity (ALPL, BGLAP, RUNX2) and osteocytes (SOST)." (PMID 29670000, 2018). "In contrast, TA treatment of 20 μM inhibited the expression of MMP2 and MMP9, the key downstream proteins that drive the EMT in prostate cancer." (PMID 29518944, 2018). "Binding of extracellular S100A4 to embigin mediates prostate cancer progression by inhibition of AMPK activity, activation of NF-κB, MMP9 and mTORC1 signaling, and inhibition of autophagy, which increase prostate cancer cell motility." (PMID 30041429, 2018). "Adipocytes derived from human peri-prostatic adipose tissue primed by prostate carcinoma cells were found to upregulate TNF-α, osteopontin, and MMP9, which are known to regulate ECM architecture." (PMID 30356678, 2018). "Recently, some results have provided new evidence that the imbalance of MMP-9/TIMP-1 is one of the regulation mechanisms to promote tumourigenicity and metastasis of prostate cancer cells." (PMID 29228747, 2017). "CRISPR/Cas9 editing of PC-3 cells showed impaired ligand-stimulated expression of MMP9, VEGF, BMP3, PSA, RUNX2, and OCN, which are involved in prostate cancer progression." (PMID 28659174, 2017). "CD44 signaling in prostate cancer cells has also been shown to regulate key proteins (i.e., RANKL and MMP9) involved in osteoclast differentiation and tumor metastasis." (PMID 28326306, 2017). "We showed that the expression level of SFMBT2 is critical for cell migration and invasion, which are fundamental features of prostate cancer malignancy through direct or indirect regulation of MMP-2, MMP-3, MMP-9, MMP-26, N-CoR, and KAI1 gene expression." (PMID 27340776, 2016). "We observed similar findings in prostate cancer lines: ELK1-shRNA strongly inhibited AR-negative cell migration/invasion and MMP-2/MMP-9 expression (unpublished data)." (PMID 26342199, 2015). "CXCL12-mediated MMP-9 expression and chemoinvasion is sensitive to PI3K inhibitors in various prostate cancer cell lines." (PMID 26204939, 2015). "In prostate cancer cells, stable expression of constitutively activated AKT (myr-AKT) induces the expression of RUNX2 mRNA and its target genes, such as PIP, PGC, MMP9 and MMP13." (PMID 26204939, 2015). "Considering the role of gelatinases in prostate cancer invasion, we also analysed the expression of MMP-2 and MMP-9 in the medium using western blotting which showed reduced expression of MMP-2 in the medium collected from PC-3WAVE-3KD cells." (PMID 26052252, 2015). "Knockdown of LCN2 suppresses the invasion of prostate cancer cells through downregulation of MMP-2 and MMP-9." (PMID 25940797, 2015). "Our results demonstrated that the expression of VEGF, and the activation of MMP-2 and MMP-9, is closely mediated by oxLDL/LOX-1 in C4-2 prostate cancer cell line." (PMID 25170920, 2014). "CXC chemokine receptor-4 (CXCR4) plays an important role in prostate cancer metastasis through the up-regulation of VEGF and MMP-9 both in vitro and in vivo." (PMID 24978435, 2014).
prostate carcinoma (continued). "Tissue microarrays of 120 archival prostate carcinoma samples were immunohistochemically evaluated for MMP-2 and MMP-9 expression and compared with clinicopathological parameters." (PMID 25097794, 2014). "In prostate cancer cells, inhibition of p300 induced apoptosis via multiple pathways, and also decreased the expression of MMP-2 and MMP-9, which reduced the migratory and invasive ability of the cells." (PMID 25523932, 2014). "In prostate cancer, MMP-2 and MMP-9 expression indicate the tumor's invasive and metastatic potential." (PMID 25097794, 2014). "In prostate carcinoma, MMP-2 and MMP-9 are novel molecular biomarkers that reflect the invasive and metastatic potential of this type of carcinoma." (PMID 25097794, 2014). "In prostate cancer, Emmprin knockdown by the siRNA led to migration and invasion through MMP-2, and MMP-9 expression." (PMID 22640183, 2012). "With the exception of work showing that the LCN2/MMP9 complex is more likely to be found in the urine of prostate cancer patients than controls, little is known about LCN2 in prostate cancer." (PMID 21649922, 2011). "MMP9 belongs to the matrix metalloproteinase family and is a target of the CXCL12/CXCR4 signaling in cancer cells, including prostate cancer." (PMID 22074556, 2011). "Together, our findings indicate that Slug positively regulates MMP9 expression, possibly via CXCR4/CXCL12 pathway in prostate cancer cells." (PMID 22074556, 2011). "During the process of prostate cancer PNI, MMP-2 and MMP-9 play an important role in degrading the matrix around the tumor and the nerve tissue." (PMID 18983683, 2008). "Our research aims to study CXCL12, CXCR4, MMP-2 and MMP-9 expression in prostate cancer PNI using in vitro experiments, animal model experiments and human prostate cancer tissue." (PMID 18983683, 2008). "In prostate cancer cells, for instance, TGF-β therapy leads to nuclear accumulation of MAPK1, which in turn promotes cancer cell EMT and upregulates the production of MMP1, MMP2/9, and MMP9." (PMID 37817112, 2023). "In pancreatic cancer, miR-301a may act as an oncogene by negatively regulating SAMD4 as its target, while in prostate cancer, miR-301a may be involved in metastasis through AR/TGF-β1/Smad/MMP9 signaling modulation." (PMID 37509289, 2023). "SIRT5 affects prostate cancer proliferation, progression and survival enhancing Acetyl-CoA acetyltransferase 1 activity leading to MAPK pathway promotion and ultimately to Matrix metallopeptidase 9 (MMP-9) and cyclin D1 expression." (PMID 35328633, 2022). "Of MMPs, MMP2 and MMP9 were the main members presented to be regulated by SKA1 and TRPV2 in some cancers, such as human adenoid cystic carcinoma, non-small cell lung cancer and prostate cancer 20-22." (PMID 35813298, 2022). "These proteins include MMP-9, which can be used as a biomarker for cancer; SPARC, an acidic secretory protein rich in cysteine, was positively correlated with CTSK expression and predicted a poor prognosis in prostate cancer and gastric adenocarcinoma." (PMID 36005209, 2022). "Furthermore, the pro-inflammatory arachidonic acid-derived prostaglandin E2 (PGE2) was shown to enhance the expression of the bone metastasis-promoting proteins MMP2, MMP9, RANKL, and RUNX2 in prostate cancer cells, partly via the PI3K/AKT pathway." (PMID 34064589, 2021). "Furthermore, through modulating the expression of MMP-9, the overexpression of TNFRSF12A can promote prostate cancer progression and result in poor treatment outcomes." (PMID 34917619, 2021). "Interestingly, while both bacterial neuraminidase and T. cruzi sialidase activate only MMP-2, the mammalian sialidase Neu-3, specific for SA α2,3 recognition observed in human prostate cancer models, is able to modulate both MMP-2 and MMP-9." (PMID 33891967, 2021).